DDX3X (DEAD-box helicase 3 X-linked)
Diseases named in the same sentence as DDX3X in open-access papers (continued):
Sharing a sentence is not in itself a finding about the gene and the disease.
Sepsis (3 papers, 2022 to 2025). Sepsis is defined as life-threatening organ dysfunction caused by a dysregulated host response to infection. "Further, the downregulation of DDX3X is associated with protective effects against the development of sepsis in mice." (PMID 39062931, 2024). "This suggests that high mortality in sepsis patients is associated with high expression of DDX3X mRNA in T cells." (PMID 35178128, 2022). "High level of DDX3X mRNA in T cells in sepsis is associated with the severity of sepsis and the mortality of patients with sepsis." (PMID 35178128, 2022). "Recent researches indicated that DDX3X is a contributing factor that leads to cell death under stress, and the reduction of cell number caused by T cell death is one of the main pathological manifestations of sepsis." (PMID 35178128, 2022). "In view of these findings, we speculated that the upregulation of DDX3X may be involved in the survival of T cells and contributes to T cell loss in sepsis." (PMID 35178128, 2022). "We therefore conducted this clinical trial and concluded that DDX3X mRNA expression level was significantly higher in patients with sepsis and septic shock than that in healthy volunteers and proved that DDX3X was associated with poor prognosis in sepsis." (PMID 35178128, 2022). "In addition, DDX3X mRNA may be a potential biomarker for predicting the risk of death in patients with sepsis." (PMID 35178128, 2022). "Our study identified DE‐PRGs—NDRG1, DDX3X, PTPRC, and TNFSF8—in patients with sepsis‐associated ARDS." (PMID 39854144, 2025). "In sepsis patients, elevated DDX3X mRNA levels in T cells correlate with T‐cell count and APACHE II score." (PMID 39854144, 2025). "The purpose of this study was to evaluate the mRNA expression level of DDX3X in T cells in peripheral blood of patients with sepsis and to explore its correlation with the prognosis of sepsis." (PMID 35178128, 2022). "In recent years, several studies have also found that DDX3X was an important regulator of cell death, including apoptosis and pyroptosis which are involved in sepsis." (PMID 35178128, 2022). "Blood samples were collected within 24 hours after the diagnosis of sepsis or septic shock, and the mRNA expression level of DDX3X in T cells was detected by PCR." (PMID 35178128, 2022). "In summary, this pilot study found that levels of DDX3X mRNA were significantly elevated in T lymphocytes of patients with sepsis and septic sepsis." (PMID 35178128, 2022). "Accordingly, in this study, we investigated the expression of DDX3X on T cells in peripheral blood of patients with sepsis and evaluated its clinical significance in sepsis." (PMID 35178128, 2022). "DDX3X mRNA expression in patients with sepsis and septic shock was significantly higher than that in the control group." (PMID 35178128, 2022). "Additionally, decreased DDX3X expression in septic ARDS patients compared to those with sepsis suggests potential immunosuppression." (PMID 39854144, 2025). "Notably, six of these genes, including GSPT2, SMCHD1, SF3B1, DDX3X, and F3, showed significant differences and consistent trends between sepsis and septic ARDS samples in the GSE66890 and GSE32707 databases." (PMID 39854144, 2025). "To evaluate the usefulness of DDX3X mRNA expression level in predicting 28-day mortality risk, we compared the predictive usefulness of DDX3X mRNA expression level, PCT, APACHE II, and SOFA in patients with sepsis by using receiver operating characteristic (ROC) curves." (PMID 35178128, 2022). "In multivariate analysis, the logistic regression model was adjusted for age, gender, lymphocyte count, PCT concentrations, the APACHE II score, SOFA score, and DDX3X mRNA in T cells to determine the relationship of 28-day mortality in patients with sepsis and septic shock." (PMID 35178128, 2022). "In addition, results showed that DDX3X mRNA level was significantly higher in the septic shock group than that in the sepsis group." (PMID 35178128, 2022).
Sepsis (continued). "As far as we are aware, this is the first report of DDX3X expression in adaptive immune cells of sepsis, which may contribute to the assessment of disease severity and prognosis." (PMID 35178128, 2022). "In view of these findings, we speculated that the expression level of DDX3X in T cells of sepsis patients may be different from that of healthy people, thus providing a potential biomarker for the diagnosis of sepsis." (PMID 35178128, 2022). "In this study, the level of DDX3X mRNA increased in T cells in patients with sepsis." (PMID 35178128, 2022). "DDX3X mRNA had the same sensitivity as PCT, but its specificity was higher than other parameters, suggesting that DDX3X mRNA could be used as a diagnostic marker of 28-day mortality in patients with sepsis." (PMID 35178128, 2022). "Therefore, the level of DDX3X mRNA on T cell may be a potential candidate for predicting 28-day mortality in sepsis." (PMID 35178128, 2022). "Additionally, we found that DDX3X expression in T cells was negatively correlated with the cell number, suggesting that DDX3X may be involved in lymphocyte depletion and immunosuppression in sepsis." (PMID 35178128, 2022). "This study identifies four key PANoptosis‐related genes (NDRG1, DDX3X, PTPRC, and TNFSF8) that are differentially expressed in sepsis and septic ARDS." (PMID 39854144, 2025). "However, it remains unclear whether DDX3X is involved in the pathological process of sepsis." (PMID 35178128, 2022). "However, the role of DDX3X in regulating adaptive immune response in sepsis inflammation has not as yet been fully understood." (PMID 35178128, 2022).
steatosis (3 papers, 2017 to 2025). Increased lipid within the cytoplasm of cells. "DEAD-box helicase 3, X-linked (Ddx3x), a member of the DEAD-box family, has been reported to regulate lipid homeostasis during hepatitis C virus (HCV)-induced steatosis." (PMID 38090607, 2023). "Previous investigation has shown that DDX3X reduces steatosis during NAFLD progression." (PMID 38090607, 2023). "Knockdown of DDX3X exacerbates HFD-induced hepatic steatosis, while further studies reveal that DDX3X ameliorates steatosis during NAFLD progression by inhibiting the mTORC1 signaling pathway." (PMID 41425091, 2025).
type 2 diabetes mellitus (3 papers, 2023 to 2025). A type of diabetes mellitus that is characterized by insulin resistance or desensitization and increased blood glucose levels. "However, a separate study reported that E3 ligase WWP2 increases DDX3X K63-polyubiquitination, promoting its proteasomal degradation in Type 2 diabetes." (PMID 41198618, 2025).
X-linked intellectual disability (3 papers, 2017 to 2023). An X-linked intellectual deficiency in which not enough information is known, reported or published to indicate whether a gene causes non-syndromic or syndromic presentations. "DEAD-box helicase 3 X-linked (Ddx3x) is an ATP-dependent RNA helicase and another cause of X-linked intellectual disability in both males and females." (PMID 36945656, 2023).
acute myeloid leukemia (2 papers, 2022 to 2025). Acute myeloid leukemia (AML) is a group of neoplasms arising from precursor cells committed to the myeloid cell-line differentiation. "Acute Myeloid Leukemia (LAML) is a life-threatening hematological malignancy, and the DEAD-box helicase 3 X-linked (DDX3X) gene is a potential yet underexplored target gene for LAML." (PMID 40564907, 2025).
Hepatic steatosis (2 papers, 2017 to 2025). Steatosis is a term used to denote lipid accumulation within hepatocytes. "Core proteins involved in SGs assembly, including G3BP1, TIA1, DDX3X, and PDCD4, have been reported to be associated with fatty liver disease." (PMID 41425091, 2025).
Hepatitis C virus (2 papers, 2022 to 2023). "Hepatitis C virus (HCV) infection induces an interaction between DDX3X and the HCV 3’ untranslated region which prompts DDX3X and IKKα to associate with stress granules." (PMID 36110852, 2022). "Evidence of the DDX3X interacts with SG in hepatitis C virus infection has been documented, suggesting that DDX3X-mediated SG formation may be important for liver pathogenesis." (PMID 37407573, 2023).
liver diseases (2 papers, 2014 to 2024). "The expression of DDX3X in patients with various liver diseases was evaluated." (PMID 39349420, 2024). "Several studies have provided evidence that DDX3X is involved in various liver diseases." (PMID 39349420, 2024).
male infertility (2 papers, 2019 to 2021). The inability of the male to effect fertilization of an ovum after a specified period of unprotected intercourse. "Heterozygous genetic lesions in DDX3X mediate a class of developmental disorders called DDX3X syndrome, while loss of DDX3Y is implicated in male infertility." (PMID 34535544, 2021).
meningioma (2 papers, 2021 to 2024). A generally slow growing tumor attached to the dura mater. "Moreover, expression levels of Beclin, LC3B, HST1, TRPV1, TRPA1, Nrf2, and DDX3X did not associate with OS of meningioma patients (p>0.05)." (PMID 38758750, 2024).
pancreatic adenocarcinoma (2 papers, 2023 to 2024). "Recently, a noteworthy finding has emerged, underscoring the indispensable regulatory role of STAU2 in pancreatic adenocarcinoma, and DDX3X was identified as its target gene." (PMID 38316768, 2024). "The output from the GEPIA tool demonstrated that DDX3X expression was consistently upregulated in most types of cancer, especially in pancreatic adenocarcinoma (PAAD), when compared to neighboring normal tissues." (PMID 38316768, 2024).
Zika virus infections (2 papers, 2021 to 2024). "We found that the ZIKV infection resulted in the accumulation of DDX3X in the nucleus (identified by the co-localization of DDX3X and DAPI nuclear staining) in BHK cells." (PMID 39009885, 2024).
anemia (1 paper, 2023). A reduction in the number of red blood cells, the amount of hemoglobin, and/or the volume of packed red blood cells. "Red blood cells are particularly sensitive to Ddx3x deletion suggesting that anemia could be a consequence of DDX3X inhibition." (PMID 37035206, 2023).
Anxiety (1 paper, 2023). Intense feelings of nervousness, tension, or panic often arise in response to interpersonal stresses. "Finally, we investigated the relevance of DDX3X variant type to anxiety and SIBs." (PMID 35536379, 2023).
Arthritis (1 paper, 2023). Inflammation of a joint. "miR-181a-5p targets to regulate the 3′ UTR of DDX3X to reduce the expression of DDX3X, thereby reducing the release of inflammatory cytokines in arthritis model cells." (PMID 37587519, 2023). "In order to understand whether miR-181a-5p can target DDX3X gene expression, thereby affecting the level of inflammatory factors in cellular model of arthritis, rescue assays were performed in this paper." (PMID 37587519, 2023).
autoimmune disease (1 paper, 2020). A disorder resulting from loss of function or tissue destruction of an organ or multiple organs, arising from humoral or cellular immune responses of the individual to their own tissue constituents. "Despite the lack of information on the association between DDX3X and autoimmune diseases and according to the current findings, the DDX3X may contribute to the pathogenesis of autoimmune diseases and female bias of autoimmunity; however, further studies are necessary to address these issues." (PMID 33297945, 2020).
B-cell neoplasm (1 paper, 2020). A group of heterogeneous lymphoid tumors generally expressing one or more B-cell antigens or representing malignant transformations of B-lymphocytes. "Next generation sequencing has revealed the presence of recurrent mutations of genes encoding several factors related to mRNA translation, including XPO1, DDX3X, RPS15 and EIF2AK3 (PERK) in mature B-cell neoplasms." (PMID 32924027, 2020).
bladder cancer (1 paper, 2024). "DDX3X, in high expression groups, demonstrated significant enrichment in bladder cancer, particularly in oxidative phosphorylation, whereas its low expression counterpart exhibited this enrichment to a lesser extent." (PMID 38965390, 2024).
chronic hepatitis B (1 paper, 2024). "To further investigate the clinical relevance of DDX3X, we analyzed DDX3X expression patterns in healthy individuals, patients with chronic hepatitis B (CHB), and patients with hepatitis B virus-associated liver failure (HBV-LF)." (PMID 39349420, 2024). "Furthermore, our results revealed a gradual increase in hepatic DDX3X expression from chronic hepatitis B (CHB) to HBV-LF, an effect that was consistent with elevated levels of ER stress markers." (PMID 39349420, 2024).
chronic myeloid leukemia (1 paper, 2022). "Interestingly, DDX3X mutations that cause alteration of protein function rather than loss of function have been described also in chronic myeloid leukemia." (PMID 35954483, 2022).
cognitive disorder (1 paper, 2024). A disease affects cognitive processes. "Mutations in DDX3X can cause DDX3X Syndrome, a cognitive disorder that was first described in 2015." (PMID 39062517, 2024). "Additionally, as an enzyme, DDX3X is potentially a specific target for therapeutics, which could decrease the long-term cognitive impairment and improve quality of life post-treatment for many patients." (PMID 39062517, 2024).
coloboma (1 paper, 2025). An abnormality in which a part of a structure in one or both eyes is missing. "A proportion of the FZD5 cases described in humans have been shown to carry variants also in other loci, and, at least in one case, compound variants of FZD5 and another gene (DDX3X) required for eye morphogenesis and leading by itself to coloboma has been described." (PMID 40401611, 2025).
Cornelia de Lange syndrome (1 paper, 2025). A rare syndrome characterized by low birth weight, delayed growth, intellectual disabillity, behavioral problems, and a distinctive facial appearance (thin, arched eyebrows, low set ears, small teeth, and small nose). "Through our four cases, we have extended the phenotypic spectra of the DDX3X, Vissers-Bodmer, 16p11.2 duplication, and Cornelia de Lange syndromes, while also adding novel genetic variants to the lists of known mutations." (PMID 41155467, 2025).
developmental disability (1 paper, 2025). Disorders in which there is a delay in development based on that expected for a given age level or stage of development. "Individuals carrying DDX3X missense mutations present with a spectrum of clinical and molecular phenotypes, encompassing neuroanatomical disruption, developmental disability, and altered biochemical activity." (PMID 39836689, 2025).
endothelial dysfunction (1 paper, 2025). In vascular diseases, endothelial dysfunction is a systemic pathological state of the endothelium (the inner lining of blood vessels) and can be broadly defined as an imbalance between vasodilating and vasoconstricting substances produced by (or acting on) the endothelium. "DDX3X overexpression promoted EndoMT as well as endothelial dysfunction and inflammation, whereas its downregulation effectively inhibited this transition in ECs." (PMID 41186241, 2025).
female infertility (1 paper, 2024). Diminished or absent ability of a female to achieve conception. "Therefore, loss of Ddx3x in mouse oocytes results in a female infertility phenotype due to apoptosis of ovarian follicles." (PMID 39551844, 2024). "Consistently, oocyte-specific Ddx3x knockout in mice resulted in female infertility and impaired oogenesis." (PMID 39551844, 2024).
hypothyroidism (1 paper, 2022). Abnormally low levels of thyroid hormone. "Our study delineated many clinical characteristics of the Chinese cohort with DDX3X variants, largely overlapping with phenotypic spectrum in previously reported studies, but hypothyroidism was first noted as a novel clinical feature." (PMID 35392274, 2022). "Although a certain degree of phenotypic overlap with previously reported cohorts, our study described the phenotypic and variation spectrum of 23 additional individuals carrying DDX3X variants in the Chinese population, adding hypothyroidism as a novel finding." (PMID 35392274, 2022). "Hypothyroidism has not been verified in animal models with in vivo depletion of Ddx3x." (PMID 35392274, 2022).
inflammatory skin disease (1 paper, 2022). Inflammatory skin disorders covers a broad category that includes many conditions ranging in severity, from mild itching to grave medical health complications These disorders are common in people of all ages and races. "DDX3X is a central decision maker in the formation of NLRP3 inflammasomes, and NLRP3 plays a vital role in inflammatory skin diseases, including psoriasis." (PMID 35277199, 2022).
ischemic stroke (1 paper, 2023). A stroke disorder caused by obstruction of blood flow to the brain, due to thrombotic (local blood clot formation) or embolic (due to a blood clot or other material traveling from another site) event. "Moreover, stress granules, DDX3X, and the NLRP3 inflammasome emerged as promising therapeutic targets for ischemic stroke treatment." (PMID 37580991, 2023). "The data suggest that SGs, DDX3X, and NLRP3 inflammasome could potentially serve as therapeutic targets for the treatment of ischemic stroke." (PMID 37580991, 2023).
kidney cancer (1 paper, 2020). Primary or metastatic malignant neoplasm involving the kidney. "Interestingly, the correlation with the favored overall survival was specifically observed in the clear cell type, which is the most malignant subtype in kidney cancer, suggesting DDX3X’s potential role as a tumor suppressor." (PMID 32326089, 2020).
Kleefstra syndrome (1 paper, 2022). A genetic disorder characterized by intellectual disability, childhood hypotonia, severe expressive speech delay and a distinctive facial appearance with a spectrum of additional clinical features. "The most represented genetic conditions were Koolen-de Vries syndrome (n = 49), Kleefstra syndrome (n = 26) and DDX3X-associated disorder (n = 11)." (PMID 36008773, 2022).
latent infection (1 paper, 2025). "In antiviral drug development, DDX3X-specific inhibitors such as RK-33, FH-1321, and the novel compound 6b block DDX3X’s ATPase or RNA-binding domains, demonstrating dual efficacy in suppressing viral replication and reversing latent infection." (PMID 40606174, 2025). "DDX3X inhibitors can inhibit virus replication and also have the potential to reverse latent infection." (PMID 40606174, 2025).
Listeria infections (1 paper, 2018). "In summary, loss of DDX3X impacts on the innate immune system both through its role in hematopoiesis and its regulation of the innate response to Listeria infections." (PMID 30475900, 2018).
liver failure (1 paper, 2024). A liver disease characterized by the liver losing or has lost all of its function. "An unexpected finding in our study was the detection of high serum DDX3X levels in immune-mediated liver injury, which was observed both in Con A-induced mice and patients with HBV-related liver failure (LF)." (PMID 39349420, 2024).
malignant mesothelioma (1 paper, 2020). A malignant neoplasm of the pleura or peritoneum, arising from mesothelial cells. "In addition, the DDX3X mutation was found in patients with malignant mesothelioma, indicating its potential role in tumorigenesis." (PMID 32326089, 2020).
Obesity (1 paper, 2025). Accumulation of substantial excess body fat. "WWP2 is an E3 ubiquitin ligase; experimental data show that reduced WWP2 aggravates diabetic endothelial injury by promoting DDX3X ubiquitination and degradation, linking obesity-related metabolic stress to endothelial barrier dysfunction." (PMID 41340073, 2025).